PLP1 (proteolipid protein 1)
Diseases named in the same sentence as PLP1 in open-access papers (continued):
Sharing a sentence is not in itself a finding about the gene and the disease.
tumor (continued). "Although it is unclear whether glia-derived WNTs are implicated in tumour formation in this model, together, these studies support the central role of the GFAP+ (but not the PLP1+) subpopulation of EGCs in intestinal epithelial health 20, 21••, 38•." (PMID 35533467, 2022). "Interestingly, myelin‐related proteins including Plp1, Mog, Mbp and Cnp were downregulated in CANReject mice compared to CANRegress mice, suggesting that hippocampal myelination may also be dysregulated in mice in which tumours did not develop." (PMID 40172096, 2025).
infection (12 papers, 2014 to 2025). The state of being infected such as from the introduction of a foreign agent such as serum, vaccine, antigenic substance or organism. "Inflammation and bacterial virulence were attenuated when PVL was antibody neutralized or when mice were infected with PVL deficient S. aureus, analogous to our observations during infection with PLP1-deficient T. gondii." (PMID 40166190, 2025). "The data presented here suggest that attenuated virulence of PLP1 knockout parasites is associated with both a control of parasite replication and the regulation of the host immune response during the acute phase of infection." (PMID 40166190, 2025). "Together these findings suggest a key role for Toxoplasma PLP1 in promoting a lethal inflammatory immune response during acute infection with a virulent strain of the parasite." (PMID 40166190, 2025). "Further studies are needed to fully probe the extent to which PLP1 impacts cellular danger recognition pathways and promotes the proinflammatory environment observed during infection." (PMID 40166190, 2025). "In vitro infection of a mixed glial population including oligodendrocytes confirmed that Plp1-OE compared to control AAV increased Plp1 mRNA overexpression in both XY and XX cells." (PMID 40043106, 2025). "In this study, we compared acute infection and host immune responses upon challenge with either WT or PLP1 knockout (Δplp1) parasites." (PMID 40166190, 2025). "Our results showed that DEGs encoding for oligodendrocytes markers genes such as Mbp, Mog and Plp1 are strongly downregulated during NF1_LV infection, suggesting oligodendrocyte damage." (PMID 39735262, 2024). "Future studies identifying other secretory proteins that contribute to egress to various degrees along with other work defining how PLP1 shapes the outcome of infection should help distinguish between these possibilities." (PMID 34190588, 2021). "In the present work we interrogated several plausible hypotheses to understand how PLP1 expression confers a virulence enhancing phenotype during infection by the parental RH strain." (PMID 40166190, 2025). "This notable distinction could be because the egress defect of Δtln4 parasites is less pronounced than that for Δplp1, or it could be due to additional roles for PLP1 during infection of mice." (PMID 34190588, 2021). "Specifically, we examined whether PLP1 knockout parasites 1) failed to disseminate throughout the host, or whether 2) they caused less overall damage at the site of infection and/or 3) induced a protective immune response that regulated parasite proliferation." (PMID 40166190, 2025). "To determine PLP1’s role during in vivo infection, we assessed whether the observed in vitro egress defect of Δplp1 parasites contributed to a failure of the parasites to replicate and establish an acute infection in vivo." (PMID 40166190, 2025). "MA10 infection induced six down-regulated (Pllp, Malat1, Myrf, Mag, Ptgds, Ugt8a) and two upregulated DEGs (Sgk1, Mbp), while Aβ pathology resulted in one down-regulated (Hmgb1) and ten up-regulated DEGs (Apoe, B2m, Clu, Cstd, Gfap, Psen1, Pllp, Cst7, Cd9, Plp1)." (PMID 41497643, 2025). "Also as before, the OL-specific genes Plp1 and Ugt8a were downregulated by infection." (PMID 37596606, 2023). "In P. monodon, two isoforms of plasmolipin, Pm PLP1 and Pmp LP2, was upregulated in haemocytes after infection with yellow head virus (YHV) and WSSV (Vatanavicharn, Pongsomboon & Tassanakajon, 2012)." (PMID 31875142, 2019). "In vivo infections demonstrate that parasites replicate, disseminate, and stimulate a protective immune response when PLP1 is not expressed." (PMID 40166190, 2025). "Using in vivo bioluminescence imaging, we show that parasites lacking PLP1 establish an acute infection and disseminate throughout the infected mice." (PMID 40166190, 2025). "Importantly, at all infectious doses, PLP1 was not required for parasites to establish acute infection and to proliferate in vivo." (PMID 40166190, 2025).
infection (continued). "Infection with PLP1-deficient parasites resulted in drastically reduced TNF-α and IL-6, resolved infection-driven IFN-γ production, and failed to result in exaggerated cytokine and chemokine responses associated with proinflammatory overproduction and host mortality." (PMID 40166190, 2025).
cancer (8 papers, 2012 to 2025). A tumor composed of atypical neoplastic, often pleomorphic cells that invade other tissues. "The cell adhesion molecules, MAPK signalling pathway, JAK-STAT signalling pathway, and cancer-related pathways were significantly enriched in the PLP1-related phenotype." (PMID 38307969, 2024). "PLP1 is also involved in cancer-related pathways and the JAK-STAT signalling pathway, and participant in tumorigenesis, maintenance, and metastasis in breast cancer." (PMID 38307969, 2024). "PLP1 has been widely reported in the formation of the central nervous system while the aberrant expression of PLP1 in various malignant tumors was identified by the bioinformatic analysis." (PMID 36386836, 2022). "More importantly, we found a number of genes commonly dysregulated in various cancers such as PLP1, MYOM1, NKAPL and USP2 which were investigated in few cancer related studies, and thus represent our novel findings." (PMID 28427185, 2017). "However, few studies have shown that PLP1, MYOM1, NKAPL, and USP2 were consistently downregulated in various cancers." (PMID 28427185, 2017). "Several genes that were highly expressed in Cluster 3 were well known to be preferentially expressed in normal oligodendrocytes, including CLDN11, MBP, PLP1, and KLK6, indicating that these cells are not cancer cells." (PMID 27368803, 2016).
neurological disease (8 papers, 2009 to 2023). "Genetic defects affecting the PLP1 gene cause the human neurological disorder X-linked spastic paraplegia type 2 (SPG2)." (PMID 33196637, 2020). "Despite the abundance of PLP in myelin, and the obvious role in neurological disease, PLP1 knockout (KO) mice have only subtle changes in myelin integrity." (PMID 24314267, 2013).
neurodegenerative disease (5 papers, 2022 to 2025). A disorder of the central nervous system characterized by gradual and progressive loss of neural tissue and neurologic function. "We observed a significant reduction in myelination-related genes (e.g., MBP, MOG, PLP1), hence confirming the pathological feature of neurodegenerative diseases." (PMID 39622637, 2025). "Mature oligodendrocytes express myelin basic protein (Mbp) and proteolipid protein 1 (Plp1) and are critical for the myelination of axons and involved in neurodegenerative diseases in brain." (PMID 35399523, 2022).
neurodevelopmental disorder (5 papers, 2020 to 2025). A behavioral and cognitive disorder with onset during the developmental period that involves impaired or aberrant development of intellectual, motor, or social functions. "Among the DEGs, strong evidence of involvement in neurodevelopmental disorders was reported for 15 of them (“definitive” gene list from SysNDD, e.g., PLP1, RGS6, and SCN3A) and moderate evidence for 10 more (“limited” gene list from SysNDD, e.g., UNC13A, NMNAT2, and CHL1)." (PMID 40182141, 2025). "Our findings demonstrate that DOP1A, as well as the DOP1A-MON2-kinesin-1 complex, could be new candidates for neurodevelopmental disorders due to the potential effect on PLP1 and MAG, which are critical to myelination, but that needs more laboratory-validation of functional and genetic evidence." (PMID 38818041, 2024).
genetic disease (4 papers, 2022 to 2025). "PMD and PMD-like diseases are rare genetic diseases that affect the central nervous system, specifically the myelin sheath and they were reported to be caused by variants in PLP1/MAG." (PMID 38818041, 2024). "In the rare genetic disorder, Pelizaeus‐Merzbacher disease (PMD), we observed that PLP1 mutations lead to a state of ferroptosis in OLs, which could be attenuated by iron chelation." (PMID 39501820, 2025).
peripheral neuropathies (2 papers, 2011 to 2022). "However, it is not specific for null-mutation patients—truncating mutations in the PLP1-specific region of exon 3 causes peripheral neuropathies and disrupts the PLP1:DM20 ratio." (PMID 35885014, 2022). "Peripheral neuropathy was noted in four patients harbouring intragenic mutations that altered RNA processing, but was absent from all PLP1-duplication patients." (PMID 21679407, 2011). "The so called "PLP1 null syndrome" is characterized by the occurrence of peripheral neuropathy that is typically absent in the other PLP1-related disorders." (PMID 21679407, 2011).
chromosomal disorder (1 paper, 2021). Clinical conditions caused by an abnormal chromosome constitution in which there is extra or missing chromosome material (either a whole chromosome or a chromosome segment). "PMD is a submicroscopic chromosomal disorder often caused by duplications of the PLP1 gene." (PMID 33429367, 2021).
mental illness (1 paper, 2025). "Pathway enrichment analysis showed proteolipid protein l (PLP1) was mainly enriched in the signaling pathway associated with mental illness, and was also involved in the long-chain fatty acid biosynthetic process (GO:0042759)." (PMID 40344088, 2025).
metabolic disorders (1 paper, 2021). "Consistently, the results revealed that dysregulation of MAG, HOXB3, MYRF and PLP1 led to metabolic disorders of sphingolipid and glutathione, which contributed to the pathogenesis of PD." (PMID 33325158, 2021).
PLP1 also shares sentences with these, for which no sentence is quoted: vascular dementia (3 papers); depression (2); amyloid (1); Angelman syndrome (1); arteriolosclerosis (1); atherosclerosis (1); atypical Rett syndrome (1); auditory neuropathy (1); autism spectrum disorder (1); autoimmune encephalitis (1); autosomal dominant optic atrophy (1); benign tumors (1); bipolar affective disorder (1); Canavan disease (1); cerebral amyloid angiopathy (1); cystic fibrosis (1); demyelination (1); disease of the brain (1); Dysmyelinating leukodystrophy (1); epilepsy (1); Friedreich ataxia (1); Graves disease (1); hyperlipidemia (1); Hypertension (1); immunodeficiencies (1); inflammatory bowel disease (1); Kennedy disease (1); leprosy (1); leukoencephalopathies (1); Lissencephaly (1).
A further 28 diseases each share a sentence with PLP1 in 1 paper.